KCNJ12 (potassium inwardly rectifying channel subfamily J member 12)
Description:
Inward rectifying potassium channel that probably participates in controlling the resting membrane potential in electrically excitable cells. Probably participates in establishing action potential waveform and excitability of neuronal and muscle tissues. Inward rectifier potassium channels are characterized by a greater tendency to allow potassium to flow into the cell rather than out of it. Their voltage dependence is regulated by the concentration of extracellular potassium; as external potassium is raised, the voltage range of the channel opening shifts to more positive voltages. The inward rectification is mainly due to the blockage of outward current by internal magnesium.
Synonyms: IRK-2; IRK2; KCNJN1; Kir2.2; Kir2.2v; hIRK1; hIRK; hkir2.2x; kcnj12x
Tractability: Small molecule: it belongs to a druggable protein family. Antibody: UniProt places it where antibodies can reach, with high confidence; its Gene Ontology location is reachable by antibodies, with high confidence; UniProt predicts a signal peptide or a membrane-spanning region.
Gene: Protein-coding gene on chromosome 17 (21,376,303 to 21,419,870, forward strand). Ensembl gene ENSG00000184185.
Subcellular location: Membrane; Cell membrane; Cell membrane, sarcolemma, T-tubule
Subcellular location (Human Protein Atlas): Golgi apparatus; Cytosol; Nucleoplasm
Pathways (Reactome):
Neuronal System: Activation of G protein gated Potassium channels; Classical Kir channels; Inhibition of voltage gated Ca2+ channels via Gbeta/gamma subunits
Muscle contraction: Phase 4 - resting membrane potential
Gene Ontology:
Molecular function: inward rectifier potassium channel activity; protein binding
Biological process: potassium ion transport; protein homotetramerization; muscle contraction; potassium ion import across plasma membrane; regulation of heart contraction
Cellular component: membrane; plasma membrane; T-tubule
Genetic constraint (gnomAD): Loss-of-function variants: 2 observed, 17.08 expected, observed/expected ratio (o/e) 0.12, 90% interval 0.047 to 0.37. The upper end of that interval is the gene's LOEUF score, 0.37, which puts it in group 1 of 6, group 1 being the genes least tolerant of losing a copy. Missense variants: 155 observed, 385.05 expected, observed/expected ratio (o/e) 0.4, 90% interval 0.35 to 0.46. Synonymous variants: 117 observed, 145.6 expected, observed/expected ratio (o/e) 0.8, 90% interval 0.69 to 0.94.
Homologues: Orthologues: macaque KCNJ12 (99% identical), guinea pig Kcnj12 (98% identical), dog KCNJ12 (97% identical), rat Kcnj12 (96% identical), mouse Kcnj12 (96% identical), tropical clawed frog kcnj12 (82% identical), zebrafish kcnj12a (79% identical), zebrafish kcnj12b (71% identical). Paralogues in human: KCNJ18 (99% identical), KCNJ2 (70% identical), KCNJ4 (65% identical), KCNJ14 (56% identical), KCNJ9 (45% identical), KCNJ3 (44% identical), KCNJ5 (44% identical), KCNJ6 (44% identical), KCNJ8 (40% identical), KCNJ11 (40% identical), KCNJ16 (39% identical), KCNJ1 (38% identical), and 3 more.
Diseases named in the same sentence as KCNJ12 in open-access papers:
KCNJ12 is named in the same sentence as 28 diseases in open-access papers, as found by Europe PMC text mining. Sharing a sentence is not in itself a finding about the gene and the disease. The quoted sentences say what the papers report.
bladder cancer (4 papers, 2016 to 2022). "Interestingly, a recent study reported that KCNJ12 acts as a straightforward target of miR-132-3p to modulate the AKT signaling pathway in bladder cancer oncogenesis and metastasis." (PMID 35935790, 2022). "For instance, hsa_circ_0014130 works as a sponge of miR-132-3p to advance the oncogenesis and metastasis of bladder cancer by regulating KCNJ12 expression, and circAGFG1 acts as a sponge of miR-195-5p to promote triple-negative breast cancer progression by regulating CCNE1 expression." (PMID 35559038, 2022). "Notably, expression of several potassium channels is modified in bladder cancer vessels vs controls (KCNC4, KCNG4, KCNS2) and in angiosarcoma vs controls (namely KCNJ16, KCNQ2, KCNJ15, KCNJ12, KCNJ1)." (PMID 27716384, 2016).
colorectal cancer (3 papers, 2021 to 2022). A primary or metastatic malignant neoplasm that affects the colon or rectum. "KCNJ12 shows high frequency of single-nucleotide polymorphisms in head and neck squamous cell carcinomas and is adopted for stratifying the stage of colorectal cancer." (PMID 34518802, 2021). "In skin development, numerous studies have shown the important roles of KCNJ12 mutations in skin cancers, such as colorectal carcinoma (CRC), head and neck squamous cell carcinoma (HNSCC), and esophageal squamosa cell carcinoma (ESCC)." (PMID 35935790, 2022).
dilated cardiomyopathy (3 papers, 2019 to 2025). Cardiomyopathy which is characterized by dilation and contractile dysfunction of the left and right ventricles. "Interestingly, a heterozygous mutation in KCNJ12 (p.Glu334del) was identified as a candidate mutation in dilated cardiomyopathy, whose mutation site is close to our results (p.G145S)." (PMID 36071494, 2022). "The expression level of KCNJ12 is also relevant to dilated cardiomyopathy (DCM), and the number of Kir2.2 channels have been observed to be decreased in DCM ventricles." (PMID 31137608, 2019).
skin cancer (2 papers, 2020 to 2022). "Over the past years, mutations of KCNJ12 have been found mainly in cardiovascular diseases and skin cancers." (PMID 35935790, 2022). "Furthermore, our analyses uncovered several recurring UV mutations following acute UVB radiation affecting multiple genes including HRNR, TRIOBP, KCNJ12, and KMT2C, which are frequently mutated in skin cancers, indicating their potential role as founding mutations in UV-induced skin tumorigenesis." (PMID 32188867, 2020).
autism (1 paper, 2015). Persistent deficits in social interaction and communication and interaction as well as a markedly restricted repertoire of activity and interest as well as repetitive patterns of behavior. "These genes with identical genomic variants included KCNJ12, MLL3, OR9G1 and PCMTD1 with different mutations reported in other disease states and appeared to reflect artifacts in the present analysis of autism." (PMID 25574603, 2015).
chronic myeloid leukemia (1 paper, 2023). "KCNJ12 encodes a potassium channel protein which is reportedly deregulated and mutated in solid cancer and chronic myeloid leukemia, respectively." (PMID 37371852, 2023).
rheumatoid arthritis (1 paper, 2017). A chronic, systemic autoimmune disorder characterized by inflammation in the synovial membranes and articular surfaces. "Furthermore, our analysis revealed drug target genes with comparable numbers of functional variants per residue, including the dofetilide target KCNJ12 (0.31 variants/residue) and the target for the rheumatoid arthritis drug niflumic acid, PLA2GLB (0.30 variants/residue)." (PMID 29273096, 2017).
cancer (8 papers, 2012 to 2025). A tumor composed of atypical neoplastic, often pleomorphic cells that invade other tissues. "Both KCNJ4 and KCNJ12 belong to the inward rectifier potassium channel family, which have been linked with cancer progression and might be valuable prognostic biomarkers and potential therapeutic targets for cancers." (PMID 37152664, 2023). "At the gene level, the large gene TTN was found most often with 2253 cancer samples, while normalized for gene length, KCNJ12 was found most often with 278 occurrences." (PMID 31189880, 2019). "So, the Cacna1d, Kcnj12 Tgfb2, Cav1, Mecom, Kitlg, and Bmp2 genes had associations with any of the five pathways of PC1 (glutamatergic synapse, cholinergic synapse, proteoglycans in cancer, pathways in cancer, and MAPK signaling pathway)." (PMID 40076966, 2025).
tumor (7 papers, 2012 to 2024). "In particular, among the genes shared in the three samples, KCNJ12 and FAM86C1P genes show significantly lower VAF in the primary tumor compared to metastases." (PMID 39409151, 2024). "Alterations in FCGBP, FLG, KCNJ12, and KCNJ18 were observed in all tumor samples." (PMID 37182141, 2023). "Conversely, a substitution in KCNJ12 was significantly enriched (p < 0.05) in the primary tumour samples from patients without recurrence, being present in 5/18 samples." (PMID 35008243, 2021). "First, alterations in FCGBP, FLG, KCNJ12, and KCNJ18 were observed in all tumor samples, regardless of the responsiveness towards HIPEC." (PMID 37182141, 2023).
KCNJ12 also shares sentences with these, for which no sentence is quoted: head and neck squamous cell carcinoma (2 papers); adenocarcinoma (1); angiosarcoma (1); aortic coarctation (1); breast infiltrating ductal carcinomas (1); cardiac disease (1); cardiac hypertrophy (1); cardiovascular diseases (1); cervical cancer (1); colon adenocarcinoma (1); colon cancer (1); infection (1); non-melanoma skin carcinoma (1); Obesity (1); prostate carcinoma (1); rhabdomyosarcoma (1); sterility (1); triple-negative breast carcinoma (1); Ventricular arrhythmia (1).